CBX3 (chromobox 3)
Diseases named in the same sentence as CBX3 in open-access papers (continued):
Sharing a sentence is not in itself a finding about the gene and the disease.
Kidney chromophobe (2 papers, 2022). "The Cox proportional risk model analysis illustrated CBX3 as a high-risk gene in adrenal cortical carcinoma (ACC), BRCA, HNSC, renal chromophobe cell carcinoma (KICH), low-grade glioma (LGG), LIHC, PAAD, and SARC." (PMID 35573019, 2022). "While the KICH (Kidney chromophobe) (P < 0.01), and PCPG (Pheochromocytoma and paraganglioma) (P < 0.05) have lower expression level of CBX3 than the corresponding control tissues." (PMID 35172803, 2022).
liposarcoma (2 papers, 2019 to 2021). A usually painless malignant tumor that arises from adipose tissue. "The expression levels of HP1-γ (CBX3) in dedifferentiated liposarcoma, myxoid/round cell liposarcoma, myxofibrosarcoma, and pleomorphic liposarcoma were upregulated by 2.270, 2.803, 2.439, and 2.785, fold for the Barretina sarcoma database." (PMID 34046352, 2021).
renal carcinoma (2 papers, 2019 to 2023). A carcinoma arising from the epithelium of the renal parenchyma or the renal pelvis. "We also found that high CBX3/HP1γ expression was associated with poor survival in patients with liver, breast, pancreatic, or renal cancer." (PMID 31375643, 2019). "Initially, we discovered that CBX3 was substantially expressed in renal carcinoma, concerning a dismal prognosis—especially in high-grade (T3 + T4) ccRCC; these findings agreed with those of earlier research." (PMID 37674204, 2023). "To validate the effect of CBX3-KD on the migration of renal cancer cells, we performed wound healing assays." (PMID 37674204, 2023).
adrenal cancer (1 paper, 2021). A carcinoma involving a adrenal gland. "Just to take one example, while not yet analyzed in adrenal cancer, CBX3 (Chrombox 3) has a similar expression pattern between the different clusters with low expression in normal and benign adrenocortical tissues and high expression in ACC, especially in the poor prognosis cluster ACC-UMAP2." (PMID 34572898, 2021).
alcoholism (1 paper, 2022). "The bubble plot of KEGG data suggested that the two pathways of “alcoholism” and “neutrophil extracellular trap formation” might be involved in the tumor pathogenesis of CBX3 to a large extent." (PMID 35172803, 2022). "Moreover, alcoholism and alteration of DNA cellular biology may be involved in the functional mechanisms of CBX3." (PMID 35172803, 2022).
atrophic gastritis (1 paper, 2021). "One study showed that the expression level of CBX3 in patients with GC and atrophic gastritis (AG) was higher than that in patients with normal gastric mucosa." (PMID 34117289, 2021).
breast tumors (1 paper, 2021). "Moreover, similar to HER2+ breast tumors, Il21 is not readily detected in B16 and NBL tumors from control or Cbx3/HP1γ-deficient mice." (PMID 34721405, 2021).
C. perfringens infection (1 paper, 2021). "Forty-eight genes in the host were upregulated with significant differences following C. perfringens infection, including top enriched CCTα, Chromobox 3, and Filamin B. Inflammation and lipid signaling are intermingled modulators of homeostasis and immunity." (PMID 34959561, 2021). "Upregulation of CBX3 in chicken small intestines post C. perfringens infection could be related to the increased activities of a cascade of cellular processes, including DNA repairing." (PMID 34959561, 2021).
clear cell renal carcinoma (1 paper, 2023). A malignant epithelial neoplasm of the kidney characterized by the presence of lipid-containing clear cells within a vascular network. "A chromobox homologue 3 (CBX3) is elevated in various cancers and significantly contributes to the promotion of malignant behavior; despite this, its exact involvement in clear cell renal cell carcinoma (ccRCC) is yet unknown." (PMID 37674204, 2023).
Cognitive impairment (1 paper, 2023). Abnormal cognition is characterized by deficits in thinking, reasoning, or remembering. "In addition, PRKCD, RASGRP1, SYNCRIP, CSNK1E, and CBX3 were involved in the regulation of synaptic plasticity and were associated with cognitive impairment caused by neurological diseases." (PMID 37106826, 2023).
colonic adenocarcinoma (1 paper, 2023). "To study the impact of HP1γ invalidation on nuclear structures, we carried out the deletion of the Cbx3 gene in the colonic adenocarcinoma cell line TC7 using the CRISPR-Cas9 gene editing technique." (PMID 37108510, 2023).
dilated cardiomyopathy (1 paper, 2024). Cardiomyopathy which is characterized by dilation and contractile dysfunction of the left and right ventricles. "These proteins are closely related to dilated cardiomyopathy (LMNA and MYH9), fibrosis (Vim), monocarboxylate transport (Slc16a1), vascular function (Cbx3 and Hnrnpn1), and endocytic trafficking (Snx5)." (PMID 39502510, 2024).
embryonal carcinoma (1 paper, 2019). A non-seminomatous malignant germ cell tumor characterized by the presence of large germ cells with abundant cytoplasm resembling epithelial cells, geographic necrosis, high mitotic activity, and pseudoglandular and pseudopapillary structures formation. "The differences in staining intensity (according to the immunoreactivity staining score (IRS)) of CBX-3 observed between seminomas and embryonal carcinomas were marked and showed a statistical significance." (PMID 31565104, 2019). "A much weaker nuclear expression of CBX-3 was seen in embryonal carcinomas (arrow)." (PMID 31565104, 2019).
endometrioid ovarian cancer (1 paper, 2020). "For endometrioid ovarian cancer patients, the CBX3 mRNA expression level was irrelevant to OS and PFS (HR = 0.35 (0.06 - 2.09), P = 0.2278, HR = 0.54 (0.21 - 1.36), P = 0.1817)." (PMID 32742466, 2020).
esophageal adenocarcinoma (1 paper, 2022). A malignant tumor with glandular differentiation arising predominantly from Barrett mucosa in the lower third of the esophagus. "The overexpression of CBX3 (HR = 3.12, p = 0.00028) and CBX8 (HR = 2.27, p = 0.035) mRNAs in esophageal adenocarcinoma patients were significantly correlated with shorter OS, whereas the overexpression of CBX7 mRNA (HR = 0.48, p = 0.039) was significantly correlated with longer OS." (PMID 35464847, 2022).
esophageal cancer (1 paper, 2022). A primary or metastatic malignant neoplasm involving the esophagus. "Given that ESCC accounts for up to 70% of EC across the world and 90% in the region known as the “esophageal cancer belt”, which includes China, we performed subsequent functional experiments in ESCC cell lines to investigate the role of CBX3." (PMID 36140750, 2022).
fibrosarcoma (1 paper, 2021). A malignant mesenchymal fibroblastic neoplasm affecting the soft tissue and bone. "With regard to the Detwiller sarcoma database, the fold-changes of HP1-γ (CBX3) expression in fibrosarcoma, malignant fibrous histiocytoma, pleomorphic liposarcoma, and round cell liposarcoma were 3.515, 3.249, 2.242, and 2.645, respectively." (PMID 34046352, 2021).
graft versus host disease (1 paper, 2022). An immune system disorder that occurs after allogeneic hematopoietic stem cell transplant and is a reaction of donor immune cells against host tissues. "However, in LUSC, SKCM, THYM, and STAD, CBX3 expression was negatively correlated with cytokine and chemokine signaling pathways, as well as several immune-related pathways, including graft-versus-host disease, natural killer cell-mediated cytotoxicity and B/T cell receptor signaling pathways." (PMID 35573019, 2022).
IgA nephropathy (1 paper, 2024). "This work shows that the CBX3, atypically expressed on the mesangial cell, is a target of IgA auto-Abs in IgA nephropathy model mice and patients." (PMID 38331476, 2024).
Infertility (1 paper, 2020). "CBX5, CBX1 and CBX3 null mutant mice revealed different phenotypic outcomes for the three isoforms: CBX5−/− mice presented a normal phenotype, CBX1−/− led to perinatal lethality, and CBX3−/− to infertility." (PMID 32545538, 2020).
laminopathy (1 paper, 2022). A rare genetic disorder caused by mutations in genes encoding proteins of the nuclear lamina. "Similar defects were also observed in vitro upon crispr/Cas9-mediated Cbx3 knockout (KO) in the TC7 enterocytic cell line, resulting in deep invaginations of the nuclear membrane detectable by electron microcopy, reflecting a laminopathy phenotype." (PMID 36400769, 2022).
liver cirrhosis (1 paper, 2019). "Among these, AFP > 20 μg/L, liver cirrhosis, tumor size > 5 cm, multiple tumors, vascular invasion, and tumor recurrence were associated with high CBX3/HP1γ expression (Chi square test P<0.05)." (PMID 31375643, 2019). "CBX3/HP1γ expression as measured in those assays was associated with malignant clinicopathological characteristics, such as AFP > 20 μg/L, liver cirrhosis, tumor size > 5 cm, multiple tumors, vascular invasion, and tumor recurrence." (PMID 31375643, 2019). "Univariate survival analysis revealed that CBX3/HP1γ expression, AFP, GGT, liver cirrhosis, tumor size, tumor number, vascular invasion, and tumor capsule were significantly associated with OS." (PMID 31375643, 2019).
lung tumor (1 paper, 2012). "High CBX3 expression has been reported in myxoid liposarcoma, colon, breast, esophageal, cervical, and lung tumor patient samples." (PMID 22870217, 2012).
metastatic melanoma (1 paper, 2026). A melanoma that has spread from its primary site to another anatomic site. "Here, we report a CBX3::ALK out-of-frame fusion identified in a case of metastatic melanoma, which produces functional ALK isoforms via alternative translation start sites." (PMID 41887222, 2026).
ovarian tumor (1 paper, 2021). "Accordingly, syngeneic ID8 or MOSE-LTICv ovarian tumor cells were injected intraperitoneally (IP) into control and Cbx3/HP1γ-deficient mice." (PMID 34721405, 2021).
papillary thyroid carcinoma (1 paper, 2025). "Additionally, CCDC32/CBX3 gene fusion has also been detected in primary tumors and metastatic lesions from papillary thyroid carcinoma patients." (PMID 39823827, 2025).
sarcoma (1 paper, 2021). A usually aggressive malignant neoplasm of the soft tissue or bone. "Another study reported that the elevated expression of HP1-γ (CBX3) was related to unfavorable OS in patients with human sarcoma." (PMID 34046352, 2021).
serous ovarian carcinoma (1 paper, 2020). "In summary, our results showed that the CBX1, CBX2 and CBX3 proteins were overexpressed in serous ovarian carcinoma tissues compared with normal ovarian tissues." (PMID 32742466, 2020). "Finally, the expression levels of CBX1 and CBX2 at the transcriptional level in serous ovarian cancer patients were related to poor OS and PFS, and CBX3 was associated with poor OS." (PMID 32742466, 2020). "In addition, serous ovarian cancer patients with elevated expression of CBX3 mRNA presented a significantly worse OS (HR = 1.25 (1.04 - 1.50), P = 0.0179) but a better PFS (HR = 0.84 (0.72 - 0.98), P = 0.0268)." (PMID 32742466, 2020). "Thus, the CBX1 and CBX2 mRNA levels in serous ovarian cancer patients were related to poor OS and PFS, and CBX3 mRNA was related to poor OS." (PMID 32742466, 2020).
small cell lung carcinoma (1 paper, 2019). Small cell lung cancer (SCLC) is a highly aggressive malignant neoplasm, accounting for 10-15% of lung cancer cases, characterized byrapid growth, and early metastasis. "In the GDS4794 data set LLM found an overexpression of Cbx3 in 23 small cell lung cancer samples." (PMID 31757200, 2019).
stomach adenocarcinoma (1 paper, 2022). "Past research reports have indicated that CBX3 expression has a positive correlation with tumor stage in patients with stomach adenocarcinoma." (PMID 35573019, 2022).
tumor (60 papers, 2012 to 2026). "The prognostic value of CBX3 is further supported by its association with tumor diameter and lymph node metastasis, suggesting its involvement in tumor growth and metastasis." (PMID 39272883, 2024). "Loss of CBX3 was associated with decreased histone lactylation and increased the prevalence of tumor cells engulfed by microglia/macrophages in vivo." (PMID 39545414, 2024). "This research also illustrated that the expression of CBX3 was linked to several tumor stages, especially between stage-I and stage-IV tumors." (PMID 35573019, 2022). "Tumor burden in Lef1- and Cbx3-Lef1-deficient animals was higher than that observed for Cbx3/HP1γ-deficient and control mice." (PMID 34721405, 2021). "ESTIMATE score demonstrated that high expression levels of LIFR, ARHGAP24, and ELOVL5 were significantly associated with lower tumor purity, whereas CBX3 exerted an inverse effect." (PMID 33463006, 2021). "The engagement of NKG2D with its ligands expressed on tumor cells likely facilitates tumor killing by Cbx3/HP1γ-deficient CD8+ effector T cells through the enhanced production of PRF1, GrB and INF-γ." (PMID 34721405, 2021). "The enhanced persistence of Cbx3/HP1γ-deficient CD8+ T cells facilitates remodeling of the tumor chemokine/receptor landscape ensuring their optimal invasion at the expense of CD4+ Tregs." (PMID 34721405, 2021). "CBX3/5/7 can regulate signaling pathways, regulate tumor immune cell infiltration, and has diagnostic value." (PMID 34966411, 2021). "NKG2D blockade resulted in uncontrolled tumor growth and decreased survival of treated animals, accompanied by the reduction of Cbx3/HP1γ-deficient CD8+NKG2D+ effector T cells in tumors, to a level similar to PBS-treated control mice." (PMID 34721405, 2021). "The ESTIMATE score, combination of stromal and immune score, indicated that high expression levels of LIFR, ARHGAP24, and ELOVL5 were significantly associated with lower tumor purity, whereas CBX3 exerted an inverse effect." (PMID 33463006, 2021). "The inability of Lef1-, Il21r-, Cbx3-Lef1- and Cbx3-Il21r-deficient CD8+ T cells to halt tumor development suggests that LEF-1 and IL-21R are necessary for their persistence in tumors." (PMID 34721405, 2021). "The increased/sustained expression of LEF-1 and IL-21R together with the enhanced effector capacity exhibited by Cbx3/HP1γ-deficient CD8+ effector T cells suggest they can persist to control tumor development." (PMID 34721405, 2021). "As a result, adoptive transfer of Cbx3/HP1γ-deficient CD8+ effector T cells alone into wild type (wt) tumor-bearing mice greatly reduces NB growth." (PMID 29225605, 2017). "Additionally, we assessed the prospective connections between the expression of CBX3 and immune invasion levels, DNA methylation, tumor mutational burden (TMB), and microsatellite instability (MSI) in 33 tumors." (PMID 35573019, 2022). "Tumor growth and production of ascites were inhibited in Cbx3/HP1γ-deficient mice compared to controls or mice ectopically expressing Cbx3/HP1γ driven by the human T-cell-restricted Cd2 promoter (Cbx3/HP1γTg)." (PMID 34721405, 2021). "Thus, after activation, Cbx3/HP1γ-deficient CD8+ T cells differentiate into effector-like cells armed with a heightened effector/killing capacity to induce tumor-cell apoptosis in vitro." (PMID 34721405, 2021). "By contrast, Ifng deletion resulted in uncontrolled NBL tumor growth in Cbx3/HP1γ-deficient mice." (PMID 34721405, 2021). "It is tempting to speculate that the imbalance of chemokine production is caused by functional alterations and/or selective expansion of tumor-associated myeloid cells imposed by Cbx3/HP1γ-deficient CD8+ effector T cells." (PMID 34721405, 2021). "In addition, CBX3 mRNA expression was found to be associated with tumor diameter and lymph node metastasis." (PMID 32894652, 2020).
tumor (continued). "Furthermore, univariate and multivariate analyses revealed that high CBX3/HP1γ expression in tumor cells was an independent and significant risk factor for shorter overall survival times after curative surgery." (PMID 31375643, 2019). "Moreover, CBX3/HP1γ expression was associated with tumor size, tumor numbers, vascular invasion, and tumor recurrence, indicating that CBX3/HP1γ plays important role in HCC cell proliferation, invasion, and metastasis." (PMID 31375643, 2019). "Our results further suggest that high CBX3/HP1γ expression in HCC tumor cells is an independent prognostic factor associated with poorer disease outcomes in HCC patients, and that CBX3/ HP1γ plays an important role in HCC tumorigenesis and progression by promoting cell proliferation." (PMID 31375643, 2019). "A recent study showed that CBX3 deficiency may mitigate the tumor burden in mice with treatment of tumor-killing CD8+ cells, further suggesting its rational role as a therapeutic target in solid tumor treatment." (PMID 29903985, 2018). "Genetic depletion of CBX3 triggered ferroptosis and substantially reduced tumor cell survival and invasiveness in two independent cancer cell models." (PMID 41540451, 2026). "Conversely, CBX3 overexpression was sufficient to promote tumor growth, migration, and invasion in vitro, and metastatic progression in vivo." (PMID 41540451, 2026). "Lactate not only impacts myeloid cells but can also induce CBX3-dependent histone lactylation within tumor cells." (PMID 41463052, 2025). "Targeting CBX3 inhibits tumor growth by both tumor cell–intrinsic mechanisms and increased tumor cell phagocytosis." (PMID 39545414, 2024). "Since histone lactylation promotes tumor growth via both tumor cell-autonomous and immunomodulatory mechanisms, we next investigated the functional role of CBX3 in tumor cell phagocytosis." (PMID 39545414, 2024). "Microglia depletion diminished the effects of Cbx3 knockdown on tumor growth and survival, a finding consistent with dual tumor cell-autonomous and immune-mediated actions of CBX3." (PMID 39545414, 2024). "Cbx3 KO increased CRC tumor chemosensitivity under IFNγ stimulation is also confirmed with MC38 syngeneic mouse tumor model." (PMID 38684864, 2024). "We finally confirmed that Cbx3 KO can increase CRC chemosensitivity under IFNγ stimulation with MC38 syngeneic mouse tumor model." (PMID 38684864, 2024). "GSEA revealed that CBX3 knockdown modulated expression of genes related to tumor escape from immune attack, KRAS signaling, IL-6 receptor-ligand interaction, and STAT3 activity." (PMID 39545414, 2024). "In loss-of-function studies, CBX3 knockdown inhibited GSC growth and sphere formation in vitro, suggesting that CBX3 has tumor cell-autonomous tumorigenic actions." (PMID 39545414, 2024). "Conversely, whereas up to 95% of NSCLC samples, which are diploid for CBX3 are also normoploid for RAC1 gene, 95% of tumor samples harboring multiple copies in CBX3 gene display low gain increase in RAC1 CN." (PMID 37633946, 2023). "Conversely, whereas the 60% of GBM samples with 2 copies of CBX3 are also normoploid for EGFR gene, all tumor samples with multiple copies of CBX3 gene display low or high gain increase of EGFR gene CN." (PMID 37633946, 2023). "In many tumor types shallow deletion and low-level copy gain for CBX3 and RAC1, and in a lesser extend for EGFR, results in a proportional manner respectively significantly lower and higher mRNA levels of the corresponding genes." (PMID 37633946, 2023).